Y_RNA (Y RNA )
Gene: Miscellaneous RNA gene on chromosome 15 (48,995,912 to 48,996,022, reverse strand). Ensembl gene ENSG00000207105.
Homologues: Orthologues: chimpanzee Y_RNA (98% identical), guinea pig Y_RNA (86% identical). Paralogues in human: RNY1 (89% identical), Y_RNA (89% identical), Y_RNA (88% identical), Y_RNA (87% identical), Y_RNA (86% identical), RNY1P11 (85% identical), Y_RNA (85% identical), RNY1P7 (84% identical), Y_RNA (84% identical), Y_RNA (83% identical), RNY1P8 (82% identical), Y_RNA (82% identical), and 97 more.